CCL19 (C-C motif chemokine ligand 19)
Diseases named in the same sentence as CCL19 in open-access papers (continued):
Sharing a sentence is not in itself a finding about the gene and the disease.
tumor (continued). "Fluorescence-activated cell sorting (FACS) analysis showed that CCL19, CCL21, and XCL1 boosted the ratios of DCs and T cells in CD45+ leukocytes while CCL3 increased the percentage of CD45+ leukocytes in total cells in MC38 tumor." (PMID 36654820, 2022). "Not coincidentally, the combination of CCL19/21 with CCL4 can also be used as an adjuvant for DNA vaccination in Her2/neu mouse tumor models." (PMID 35770088, 2022). "Our study on the CCL19/CCR7 axis showed higher levels of CCR7 mRNA expression in NSCLC samples compared to macroscopically unchanged lung tissue (control tissue), surrounding the tumor." (PMID 35160116, 2022). "CCL3, CCL19, CCL21, and XCL1 exhibited potent anti-tumor activities in vivo, although they might differentially regulate immune cells in the TME and antigen transfer to lymph nodes." (PMID 36654820, 2022). "It has been reported that CCL19, as a chemokine, can promote the release of cytokines by CD8+ T cells by binding to its receptor CCR7, thereby inhibiting the proliferation, migration, and invasion of tumor cells." (PMID 36189258, 2022). "Mouse tumor tissues and adjacent tissues were taken for RT-qPCR analysis targeting hCCL19 to confirm that CCL19 was expressed by tumor tissues rather than by adjacent cells." (PMID 34527749, 2021). "Interestingly, CCL7, CCL19, CXCL7, NRG3, SLPI, OPN, and HGF in macrophages are upregulated in response to increased tumor CCL5 expression." (PMID 34298673, 2021). "Except for an inverse relation between CXCL2 and CCL19 in non-transformed tumor-adjacent tissue, all of the correlations between the chemokine genes were positive." (PMID 34885960, 2021). "The main population of TAMs comprises CD163+ M2 macrophages, and CD163+ TAMs release soluble (s)CD163 and several proinflammatory chemokines (CXCL5, CXCL10, CCL19, etc.)as a result of TAM activation to induce an immunosuppressive tumor microenvironment together with other immunosuppressive cells." (PMID 32707850, 2020). "In addition, adipocytes increase C–C motif chemokine ligand 19 (CCL19) and CCL21 expression in LECs and C–C chemokine receptor type 7 (CCR7) expression in tumor cells, which attracts more tumor cells to the lymphatic vessels." (PMID 33203856, 2020). "Furthermore, CCL19/CCR7, CXCL12/CXCR4, and CCL20/CCR6 were shown to be potential new targets for tumor gene therapy in type 2 PRCC." (PMID 32775427, 2020). "Nevertheless, if the tumor microenvironment has favorable conditions for tumor development, then CCL19 and CCL21 may participate in Treg recruitment to the tumor niche." (PMID 33076281, 2020). "The high expression of CCL19 and CCL21 in TIL-rich cancers suggests that these chemokines play important roles in attracting T cells, NK cells and mature dendritic cells into the tumor tissues." (PMID 30967156, 2019). "So we hypothesized that the CCL19 secreted by CRC cells predominantly combined with CCR7 expressed by HUVEC and affect tumor angiogenesis." (PMID 30250188, 2018). "To determine whether CCL19 is involved in CRC angiogenesis in vivo, we constructed subcutaneous xenotransplanted tumor models." (PMID 30250188, 2018). "Taken together, these results indicated that CCL19 can reduce the ability of HUVEC on proliferation, migration, and sprouting responses which may be able to suppress tumor angiogenesis in vivo." (PMID 30250188, 2018). "CCL19 mRNA and protein expression were significantly higher in tumor group than in noncancerous tissue group (p < 0.01)." (PMID 29088748, 2017). "Moreover, we demonstrated that CCL19‐induced AKT phosphorylation; however, CCR7 siRNA suppressed CCL19‐induced AKT phosphorylation, a key regulator of tumor metastasis." (PMID 28378417, 2017). "Moreover, ascophyllan treatment induced up-regulation of CCR7 in DCs and its ligands CCL19 and CCL21 in spleen in tumor-bearing mice." (PMID 27008707, 2016).
tumor (continued). "It is noteworthy that our study, suggesting the enhanced CCL19-induced chemotaxis of TNBC-affected DCs, is an alternative perspective on tumor evasion strategies, where tumors may manipulate host adaptive immune responses via accelerated migration of DCs." (PMID 27451948, 2016). "In another study focusing on human endogenous retrovirus antigen H (HERV-H) that is frequently and highly expressed in metastatic tumor cells, we also found that CD45−CD271+ MSCs are specifically recruited by CCL19 released from HERV-H+ tumor cells in the microenvironment." (PMID 25883937, 2015). "CCL19 has also been shown to occur in low expression in spleens of hosts without the presence of a tumor." (PMID 26497558, 2015). "Only two of the 44 significant genes (PMEPA1 and CCL19) from our cancer/neoplasia/normal classification analysis are not significant in the TCGA dataset (adjusted P-values >0.05)." (PMID 24887547, 2014). "Categorizing tumors by the expression of either tumor-derived CXCL13, CCL19, CCL21, LTαβ or their key master regulators, such as the IRFs, may allow us to stratify patients more easily into IR+ or IR− subtypes." (PMID 24762633, 2014). "In a similar manner, induced expression or ectopic delivery of LTβR downstream mediators, CCL19 or CCL21, in the TME results in inhibition of tumor growth or complete rejection of established tumors associated with increased infiltration by CD3+CCR7+ T cells and/or DCs in a range of cancer models." (PMID 24348473, 2013). "CCL19, a ligand of CCR7, was expressed on tumor cells in 109 tumor samples (53%)." (PMID 21624121, 2011). "In ELISA test for CCL19 and CCL22 of various CIK groups, it was founded that k-ras-DCs can apparently enhance CIKs' migration activity and can improve their migration capacity towards tumor cells." (PMID 22347323, 2011). "Compared to diluent-treated controls, the treatment group receiving CCL19 had a significant increase in type 1 cytokines (GM-CSF, IFN-γ) and antiangiogenic chemokines (CXCL9, CXCL10) and a decrease in the immunosuppressive cytokine TGF-β at the tumour sites." (PMID 16598185, 2006). "As lower expression of Lyve1 in tumor sites was identified by spatial transcriptomics analysis in this study and lymphatic angiogenesis was often driven by VEGF-families, we subsequently explored the correlation of VEGF-families with CCL21, CCL19, Pecam1 (CD31) and Lyve1 by the TCGA database of HCC." (PMID 40685403, 2025). "The observed positive correlation between CCL19 and activated CD8 T cells in this study reflects the host’s anti-tumor immune response, while also indicating that the balance between the tumor and immune system may be disrupted, potentially influencing BC progression." (PMID 40895068, 2025). "Diverse components of the interferon-enriched community including LAMP3+ DC, CCL19+ fibroblast, CXCL9+ macrophage, and mesenchymal-derived interferon states confer favorable responses to immunotherapy and form different ecosystems between tumor, adjacent normal, and healthy normal tissues." (PMID 38744958, 2024). "We selected CCL19 as APC binding molecule for further characterization based on its ability to increase the immunogenicity of the fused neoepitopes inducing a balanced neoepitope-specific CD4+ and CD8+ T-cell responses and leading to complete tumor rejection in a prophylactic setup." (PMID 37720215, 2023). "Our previous studies indicated that gene modification to express IL‐7 and CCL19 in antitumor effector T cells, such as CAR‐T and TCR‐T cells, profoundly enhances therapeutic effects for solid cancers by inducing a massive infiltration of immune cells in tumor tissues and long‐term memory responses." (PMID 37031457, 2023). "Therefore, the potent tumor-suppressive effects of CAR-T cells expressing CCL19 are unlikely to be directly derived from CCL19." (PMID 35990619, 2022). "Subsequently, we investigated whether CCL19 expression in the mesoCAR-N19 cells can be induced by mesothelin-positive or negative tumor cells." (PMID 35990619, 2022).
tumor (continued). "It has been reported to abnormally express in diverse tumor types and has been blamed for enhancing tumor migration, epithelial mesenchymal transition (EMT) and cancer stemness through combination with its two CC motif ligands: CC chemokine ligand 19 (CCL19) and CC chemokine ligand 21 (CCL21)." (PMID 35904690, 2022). "In addition, the highest CCL19 mRNA expression level was noted in a case of a patient with a pTNM stage T1 primary tumor, without metastasis to lymph node (N0)." (PMID 35160116, 2022). "In vivo studies showed that CCL19 overexpression within the tumor could effectively recruit CAR-T cells targeting GPC3, an HCC-specific antigen, to infiltrate tumor tissue and better inhibit tumor tissue growth." (PMID 34527749, 2021). "Moreover, these genes may play important roles in promoting tumor angiogenesis (CXCL13, ZAP-70, and CCL19), tissue remodeling (ITGAM and ITGB2), and immunosuppression (CD4 and IL-10) in cancer cell lines or samples." (PMID 32509861, 2020). "Although the function of CCL19/CCR7 on tumor angiogenesis has been confirmed in our study, it is difficult to translate the results obtained in experiments to human disease treatment, and the internal mechanisms of tumor angiogenesis still require to be further studied." (PMID 30250188, 2018). "Similarly, the over-expressed chemokines CCL19 and CCL21 may be expressed by the tumor cells, whereas their CCR7 receptor may be expressed by licensed DC or (less typically) by naive and central memory T cells." (PMID 27386846, 2016). "Interestingly, distinct effects on virus activity were also observed, in which VV expressing CCL5 or CCL19 resulted in increased persistence within the tumor and more rapid clearance from non-tumor tissues, respectively." (PMID 24967214, 2014). "Perhaps the most compelling evidence that tumor-derived chemokines influence the type of DCs found in the tumor has been demonstrated in a renal-cell carcinoma model, where the intra-tumoral or peri-tumoral distribution of DCs is determined by CCL20 and CCL19 levels." (PMID 24339824, 2013). "Notably, CCL19 overexpression induced higher ratios of tumor-infiltrating conventional CD4+ T and NK cells but fewer Treg cells compared to CCL21, which may partially contribute to the more prominent anti-tumor effect of CCL19." (PMID 36654820, 2022). "GPC3 CAR-T cells were injected via the tail vein into tumor-bearing mice treated with or without AAV-CCL19 for 7 days to further verify whether the better antitumor effect produced by the combination of CAR-T cells and AAV was due to the chemotactic effect of CCL19 on T cells." (PMID 34527749, 2021). "Notably, tumor cells expressed relatively high levels of chemokines (e.g., CCL20, CCL19, and CXCL10), while the corresponding receptors were widely expressed in immune cells, suggesting that these chemokines play significant roles in enhancing immune cell infiltration into NPC tumor tissue." (PMID 32686767, 2020). "CAR‐T cells in this model, it is not necessarily due to the presence of IL‐7 and/or CCL19 since 7 × 19 CAR‐T cells could produce a comparable or even higher IFN‐γ when 7 × 19 CAR‐T cells generated from a different donor were co‐cultured with a different tumor (data not shown)." (PMID 37031457, 2023). "Although ceRNA network has been verified in a variety of tumor cells, the ceRNA network of CCR7/CCL19 chemokine axis in BC has not been studied." (PMID 37864213, 2023). "The constructs harboring CCL4 and CCL19 as APC-binding molecules were the most efficient, with CCL19_Neo5 leading to statistically significant tumor control compared to the non-targeted construct NT_Neo5." (PMID 37720215, 2023). "Besides, CCL5, CCL19 and CXCL9 were positively correlated with CD8+ T cell infiltration assessed by QUANTISEQ (Rho = 0.818, 0.578, and 0.716, respectively), which suggested that a high expression of CCL5, CCL19, and CXCL9 might promote the tumor infiltration of CD8+ T cells in CL-BCa." (PMID 35359417, 2022).
tumor (continued). "Only CCL19 and CXCL2 were not upregulated in tumors, nor was CXCL2 in tumor-adjacent tissue compared to normal mucosa." (PMID 34885960, 2021). "The non-paired analysis confirmed significantly higher CCL19 and significantly lower CCL4 and CXCL2 expression in tumor-adjacent tissue than in tumors, and a lack of difference in the case of CCL3." (PMID 34885960, 2021). "CCL19 and CXCL11 were not differentially secreted in the tumor (1221.47 ± 250 pg/ml and 69.1 ± 9 pg/ml, respectively) compared to the adjacent tissue (1399.5 ± 300 pg/ml and 34.6 ± 5 pg/ml, respectively)." (PMID 31105699, 2019). "Global transcriptome studies on the spleen with and without the impact of the tumor surprisingly revealed up-regulated immune related functions in old hosts with CD2, CD3ε, CCL5, and CCL19 being key T-cell related factors." (PMID 26497558, 2015). "Tumors with brisk/non-brisk tumor-infiltrating lymphocytes (TIL) vs. absence of TIL exhibited significantly higher levels of APRIL/TNFSF13 (p = 0.01), CCL19 (p = 0.01) and CXCL13 (p = 0.01), but no such difference was observed for patients’ serum levels of CXCL10 (p = 0.97)." (PMID 37435077, 2023). "We treated ER+ tumor cells (MCF7) with fulvestrant in the presence or absence of the top five secreted cytokines (GROα/CXCL1, IL-8, CXCL5, hepatocyte growth factor (HGF) and CCL19)." (PMID 37423299, 2023). "In tumour types where regional delivery in not a feasible strategy, armouring of CAR T-cells with an appropriate chemokine (e.g., CCL19) or chemokine receptor can increase efficiency of tumour delivery, an approach that has boosted both efficacy and safety in pre-clinical testing." (PMID 36829563, 2023). "The reason may well be that CCL19 and CCL21 function better in the tumor progression rather than the tumorigenesis process of HCC, and DEN/CCl4-induced tumor models are not strongly consistent due to individual differences among mice and the sample sizes." (PMID 35673582, 2022). "Therefore, if the CAR-T cells were programmed to chronically overexpress CCL19, it would not be able to efficiently recruit other CAR-T cells or immune cells to specifically infiltrate the tumor tissue." (PMID 35990619, 2022). "Additionally, immature DC, when infused, will not traffic to the tumor like mature DC’s do, as fully mature DCs upregulate CCR7 and respond to CCL19 chemotaxis." (PMID 33513928, 2021). "Moreover, CCL19/CCL21 were found in tumor infiltrates of cHL, whereas the tumor nodules in NLPHD almost completely lacked these chemokines." (PMID 34778050, 2021). "Therefore, if CCL19 expression is chronically upregulated by CAR-T, then chemotaxis may become inefficient, since these CAR-T would then also home towards other tissues non-specifically instead of exclusively to the tumor tissues." (PMID 35990619, 2022). "In addition, PF4 and PPBP may function as tumor suppressors in cirrhotic HCC, meanwhile, CCL19 may act as a protective factor in non-cirrhotic HCC, while miRNAs regulate mechanisms still unclear, further experimental trials are still need to be launched in the future." (PMID 31346321, 2019).
cancer (114 papers, 2006 to 2026). A tumor composed of atypical neoplastic, often pleomorphic cells that invade other tissues. "The expression levels of six chemokine genes (CCL5, CXCL9, CXCL13, CXCL10, CXCL11, and CCL19) were significantly associated with the image-based immune scores across all 13 tested cancer types." (PMID 34030676, 2021). "Chemokines and growth factors and their receptors are known to mediate chemotaxis of cancer cells and cancer-associated stromal and inflammatory cells, e.g., CCL19- and CCL21-CCR7 and FGF-FGFR." (PMID 27391808, 2016). "Based on the single‐cell sequencing derived from NPC clinical samples, RANBP17 is expressed in EBV‐associated NPC cells, KCNJ10 is detectable in myeloid cells, and CXCR5 is dormantly expressed by B cells, while cancer‐associated fibroblasts mainly express CCL19 and CCL21." (PMID 41397929, 2025). "Additionally, ELISA analysis was employed to assess the alteration in CCL19 secretion in cancer-associated fibroblasts (CAFs) and macrophages." (PMID 38300311, 2024). "In previous studies, CCR7/CCL19 was reported to be associated with some types of cancer." (PMID 34544443, 2021). "Therefore, a possible role of CCR7 in cancer development and metastasis is its association with cancers, as well as being linked to the expression of its ligands, CCL19 and CCL21." (PMID 22251626, 2012). "At the transcriptomic level, we found that CCL19 and TRAF3IP3 were protective factors in pan‐cancer, whereas IL11, PTGES, and TNFAIP3 were risk factors." (PMID 40714831, 2025). "The thymus of mice with cancer cachexia exhibited degradation of the thymic medulla and decreased expression of LtβR, Mmp9 and Ccl19 in thymus medullary fibroblasts (mFbs)." (PMID 40665793, 2025). "Dysregulated expression of CCL19 and its receptor CCR7 has been widely implicated in various cancers." (PMID 40895068, 2025). "CCL19 is a crucial chemotactic factor involved in regulating both physiological conditions and pathological situations, including cancer." (PMID 40072746, 2025). "The genetic characterization of 12 chemokines in TLS, particularly CCL19, CCL21, and CXCL13, has been linked to increased survival in patients with BC, CRC, and other cancers." (PMID 40038799, 2025). "CPSCs differentiated into CCL19+ TPSCs in immune‐enriched regions, MYH11+ TPSCs in the stromal region, and PLXDC1+ TPSCs, which exhibited cancer‐associated myofibroblasts (myCAFs) phenotype linked to poor prognosis." (PMID 40091495, 2025). "This study identified PSCA as a risk gene (hazard ratio > 1) for BRCA, while FREM1, NPY1R, CCL19 and CLIC6 were the protective genes for the cancer (hazard ratio < 1)." (PMID 39119106, 2024). "Alternatively, this study sought to demonstrate that DPT enhances immune infiltration via CCL19 and improves patient prognosis, while CAFs primarily promote cancer in the TME." (PMID 38300311, 2024). "The CCL19/C-C motif chemokine receptor (CCR) 7 axis poses an anti-cancer property that both CCL19+ DCs and CCR7+ DCs augment CD8+ T cell immunity." (PMID 39114657, 2024). "Further research into the complex interactions involving CCL19 in different cancer types will likely yield valuable insights for cancer diagnosis, prognosis, and treatment strategies." (PMID 37944262, 2023). "This systematic evaluation provides a foundation for elucidating the role of CCL19 as a prognostic marker in cancer and its implications for patient outcomes across different cancer types." (PMID 37944262, 2023). "CCL19 plays a significant role in cancer research by influencing immune cell recruitment, activation, and the formation of tertiary lymphoid structures within the TME." (PMID 37944262, 2023). "We meticulously analyzed these trends within specific cancer categories to gain insights into the potential prognostic value of CCL19 expression." (PMID 37944262, 2023). "The results designated CCL19 as the most promising APC-binding molecule for delivering in silico-predicted cancer neoepitopes, closely followed by CCL4." (PMID 37720215, 2023).